FGFR2 (fibroblast growth factor receptor 2)
Diseases named in the same sentence as FGFR2 in open-access papers (continued):
Sharing a sentence is not in itself a finding about the gene and the disease.
gastric cancer (continued). "Moreover, we demonstrated that targeting ILK increased the effectiveness of FGFR inhibition for gastric cancer with FGFR2 amplification." (PMID 31076567, 2019). "Some gastric cancers have FGFR2 amplifications, making them sensitive to FGFR inhibitors." (PMID 31076567, 2019). "In addition, the fibroblast growth factor receptor 2 (FGFR2) ACSL5 chimera RNA rendered clinical gastric cancer cells resistant to treatment with FGFR inhibitors." (PMID 31053784, 2019). "FGFR2 amplifications can be detected in triple negative breast (4%) and gastric cancer (4%-7%)." (PMID 35582593, 2019). "One can speculate that focusing on these rare gastric cancer patients with high homogenous FGFR2 expression may have resulted in higher efficacy for AZD4547." (PMID 28852882, 2018). "FGFR2 is overproduced in gastric cancers and in triple negative breast cancers." (PMID 30577533, 2018). "In addition to the lncRNAs, we also profiled the expression pattern of identified candidate gastric cancer-associated genes EGFR, FGFR2, KLF4, DNMT1 and AGO4 shortlisted from the analysis of genes by relative quantification." (PMID 29719612, 2018). "Regorafenib may be a potential candidate for treatment against FGFR2‐amplified colorectal and gastric cancers." (PMID 29573334, 2018). "Surprisingly, these samples also showed a more homogeneous FGFR2 expression within the tumor sample, suggesting that FGFR2 gene amplification might have been an early event in the development of these gastric cancer cases." (PMID 28852882, 2018). "FGFR2 has been proposed as a target for the treatment of gastric cancer." (PMID 28852882, 2018). "Fibroblast growth factor receptor (FGFR2) has been proposed as a target in gastric cancer." (PMID 28852882, 2018). "Hence, there is significant interest in FGFR2 as a therapeutic target for FGFR2‐amplified gastric cancers, and preclinical and clinical evaluation of FGFR inhibitors are actively ongoing." (PMID 29573334, 2018). "RNAscope and DISH are suitable methods to evaluate FGFR2 status in gastric cancer." (PMID 28852882, 2018). "Different methodologies have been used to analyze FGFR2 expression and gene amplification in gastric cancer: Southern blot analysis, comparative genomic hybridization, quantitative real-time polymerase chain reaction (qPCR), and fluorescence in situ hybridization (FISH)." (PMID 28852882, 2018). "FGFR2 is also amplified in gastric cancers (5–10%) and a small subset of breast cancers." (PMID 30404198, 2018). "Clinical evaluation of regorafenib in FGFR2‐amplified colorectal and gastric cancers is warranted." (PMID 29573334, 2018). "Three of nine FGFR2-amplified patients with gastric cancer responded to AZD4547." (PMID 30404198, 2018). "A pan-HER inhibitor, PF0029984, was tested in seven gastric cancer cell lines, each having one of the following abnormalities: KRAS mutation; amplification of FGFR2, MYC (V-Myc avian myelocytomatosis viral oncogene homolog) or MET (MET proto-oncogene receptor tyrosine kinase)." (PMID 29872697, 2017). "We also proved that SPRY2 could inhibit FGFR2-induced ERK phosphorylation and suppress FGFR2-elicited gastric cancer cell proliferation and invasion." (PMID 28002800, 2017). "FGFR2 is the only well-defined prognostic biomarker in gastric cancer among FGFR family." (PMID 28002800, 2017). "As preclinical data suggest that FGFR2-amplified gastric cancers respond to targeted inhibitors, clinical trials where patients selected for FGFR2 amplification or polisomy are treated with inhibitors such as Dovitinib (NCT01719549) or AZD4547 (NCT01457846) are ongoing." (PMID 28915702, 2017). "Approximately 4-7% of gastric cancers show FGFR2 amplification, which may correlate with poor prognosis of gastric cancer patients." (PMID 28292264, 2017). "Thus, it has become increasingly apparent that FGFR2 is a potential therapeutic candidate for gastric cancer." (PMID 28292264, 2017).
gastric cancer (continued). "Furthermore, inhibition with AZD4547 resulted in a significant dose-dependent tumor growth inhibition and survival of gastric cancer carrying an FGFR2 gene amplification both in vitro and in vivo." (PMID 28030802, 2017). "Hence, FGFR2 amplification is a questionable predictive marker for the response to FGFR2 inhibitor alone in metastatic or unresectable gastric cancer." (PMID 27802183, 2017). "However, current results are distinct from those of studies on resectable gastric cancer, which reported a relationship between FGFR2 amplification and poor prognosis." (PMID 27802183, 2017). "In summary, above observations suggested that FGFR2 could facilitate cell proliferation and invasion in gastric cancer, and SPRY2 functioned as an antagonism in this process." (PMID 28002800, 2017). "Preclinical, in vitro, and in vivo studies suggest that breast and gastric cancer cell lines with FGFR2 amplifications may be sensitive to FGFR inhibitors; clinical trials are ongoing." (PMID 28835367, 2017). "Although FGFR2 amplification is associated with poorer OS, it does not appear to be an independent prognostic predictor in patients with advanced gastric cancer treated with palliative fluoropyrimidine and platinum chemotherapy." (PMID 27802183, 2017). "The FGFR2 mRNA in adjacent tissues was remarkably lower than in tumor and lymphatic tissues, indicating FGFR2 could facilitate gastric cancer oncogenesis and invasion." (PMID 28002800, 2017). "Additionally, high expression levels of FGFR1, FGFR2, or FGFR4 are associated with tumor progression and poor survival in patients with gastric cancer." (PMID 26993773, 2016). "Up to 10 % of primary gastric cancers are characterized by FGFR2 amplification, and fibroblast growth factor receptor (FGFR) inhibitors may represent therapeutic agents for patients with these malignancies." (PMID 25407459, 2016). "Despite their suggested importance, the mechanistic roles of FGFR2 and gastric cancer stem cell (GCSC) marker CD44 remain unclear." (PMID 27107424, 2016). "Moreover, in situ FGFR2 expression in patient-derived gastric cancer tissue correlated with tumorigenic potential in a xenograft model." (PMID 27107424, 2016). "The effectiveness of FGFR inhibitors against gastric cancer in vitro and in vivo suggests that the use of these compounds may be a therapeutic strategy for the selected group of patients with FGFR2-amplified gastric cancer." (PMID 25407459, 2016). "For that purpose the FGFR2 amplified gastric cancer cell line Kato-III was used." (PMID 26036639, 2015). "Finally, FGFR2 is well known as an alternate oncogene that can be molecularly targeted in gastric cancer 47,48." (PMID 25154973, 2015). "FGFR2 amplification was observed in 4.1% of gastric cancers and our established PCR-based copy number assay could be a powerful tool for detecting FGFR2 amplification using FFPE samples." (PMID 22240789, 2012). "These compounds are also known to have a potential kinase inhibitory effect on FGFRs, indicating that the development of these multi-kinase inhibitors may be a promising approach to the treatment of FGFR2-amplified gastric cancer." (PMID 22240789, 2012). "It has been suggested that FGFR2 plays an important role in the tumorigenesis of gastric cancer." (PMID 22292069, 2012). "FGFR2 amplification confers hypersensitivity to FGFR inhibitor in gastric cancer cell lines." (PMID 22240789, 2012). "Finally, FGFR2 over expression and amplification has been observed in a small proportion of gastric cancers (scirrhous) and inhibitors have shown some efficacy in clinic." (PMID 21781349, 2011). "A translational clinical trial demonstrated that tumors with high-level clonal FGFR2 gene amplification showed response to treatment (four out of nine patients with FGFR2-amplified gastroesophageal cancer), although the sample size for the gastric cancer cohort was limited." (PMID 41303727, 2025).
gastric cancer (continued). "FGFR2-positive circulating tumor cells were significantly correlated with FGFR2 overexpression and gene amplification in the surgical specimen of a gastric tumor, which validates a potential liquid-biopsy-based approach towards screening and monitoring for FGFR2-amplified gastric cancer." (PMID 41303727, 2025). "We further observed that FGFR2 fusion models, including gastric cancer cell lines, were sensitive to CA3 inhibition, and surprisingly, CA3 exposure was associated with upregulation of an androgen receptor associated transcriptional signature in the tested CCA and gastric cancer models." (PMID 39300603, 2024). "Similarly, in a single arm phase II study of nintedanib in patients with refractory oesophago-gastric cancers, 6 of 32 patients (19%) were progression-free at 6 months, however, FGFR2 alterations (which were detected in 18% of patients), were not predictive of progression-free survival (PFS)." (PMID 38791079, 2024). "FGFR2 mutations and fusions are not exclusive to gastric cancer." (PMID 39195304, 2024). "Indeed, this response in advanced solid malignancy, as well as preclinical data in FGFR2-amplified gastric cancers to dovitinib, sparked the GASDOVI phase II clinical trial investigating dovitinib in FGFR2-amplified gastric cancer; the result of this has yet to be publicly reported." (PMID 39195304, 2024). "Furthermore, some molecules act by regulating the levels of FGFR2 in gastric cancer." (PMID 37750089, 2023). "Background: c-mesenchymal epithelial transition factor receptor (c-MET) and fibroblast growth factor receptor 2 (FGFR2) amplification have been identified as factors associated with advanced stage and poor prognosis in gastric cancer (GC)." (PMID 38137393, 2023). "However, the proportion of FGFR2-amplified tumors in the overall cohort was slightly higher in the group of gastric carcinomas with intestinal histology (13/187, 7.0%) than that of tumors with diffuse morphology (13/225, 5.1%), possibly due to the distribution of the investigated subtypes." (PMID 36416959, 2023). "Three receptor tyrosine kinases (RTKs), MET, ErbB2, and FGFR2, have been widely studied in gastric cancer (GC)." (PMID 35884507, 2022). "Of all cancer types screened, gastric cancer (GC) was the most common cancer type with FGFR2 amplification (87.5% of all FGFR2 amplification case) or fusion (46.7% of all cases)." (PMID 35342406, 2022). "Gastric cancer cases with focal gene amplification of HER2 and FGFR2 in different parts of the tumor tissue have been reported, which might lead to insufficient clinical activity or resistance of targeted therapies in gastric cancer." (PMID 28852882, 2018). "In this study, we demonstrated that inhibition of FGFR signaling in FGFR2‐amplified cancers might be one of the mechanisms of antitumor activity demonstrated in preclinical and clinical evaluation of regorafenib in colorectal and gastric cancers." (PMID 29573334, 2018). "In the current study, we aimed at revealing the function of DDX6 in HER2 and FGFR2 related human gastric cancer (GC) by using clinical samples and GC cell lines." (PMID 29987267, 2018). "Similarly, FGFR2 amplification has been found in triple-negative breast and gastric cancers." (PMID 30326595, 2018). "The frequency of FGFR2 amplification in gastric cancer (GC) varies from 2 to 9%, with MET and HER2 amplifications being mutually exclusive with FGFR2 amplification." (PMID 28122360, 2017). "Although MSI-H gastric cancers are hyper-mutated, MSS gastric cancers also possess a high frequency of genetic alterations such as CDH1, RHOA, HER2, EGFR, VEGFR, MET, and FGFR2, all of which may directly or indirectly affect the MAPK and PI3K/Akt survival pathways." (PMID 29137273, 2017).
gastric cancer (continued). "Given this, to predict the mechanisms of acquired resistance which may emerge in patients with FGFR2-dependent gastric cancer following treatment with selective FGFR inhibitors, we generated three SNU-16 cell lines resistant (SNU-16R) to AZD4547, BGJ398, and PD173074, respectively." (PMID 25407459, 2016). "Among the 16 primary GC masses from which tumorigenic patient-derived gastric cancer xenograft (PDGCX) cell lines were derived, 14 primary GC masses (87.5%) highly expressed FGFR2 (FGFR2+/hi)." (PMID 27107424, 2016). "In the case of gastric cancer (GC), FGFR2 protein overexpression by immunohistochemistry was reported to be 30–40%, while the incidence of FGFR2 amplification varies from 3–10%." (PMID 25576915, 2015). "Scirrhous gastric cancer is known to be refractory to intensive treatment and to carry a poor prognosis; however, FGFR2 amplification is found in cell lines originating from scirrhous GC, such as KATO-III, SNU-16, and OCUM-2M." (PMID 26000013, 2015). "Notably, the patients in the analysis of FGFR2 amplification were all gastric cancer patients." (PMID 25171497, 2014). "Therefore, the evaluation of both the HER2 and FGFR2 status before anti-cancer treatment may be needed in gastric cancer patients in the near future." (PMID 22240789, 2012). "However, very limited information on FGFR2 amplification is available regarding the frequency, the degree of the increase in the copy number, the histology and a high-throughput screening method in gastric cancer." (PMID 22240789, 2012). "RNA helicase DDX6 was also identified as playing a role in the post-transcriptional regulation of both FGFR2 and HER2 in gastric cancer cells." (PMID 41303727, 2025). "We also identified FGFR2 as a context-dependent candidate, with marked activation in KATOIII and SNU-16 (gastric carcinoma)." (PMID 41035678, 2025). "FGFR2 gene amplification is the most common aberration (2–9%), which leads to FGFR2 protein overexpression and FGFR pathway constitutive activation in gastric cancer." (PMID 38255923, 2024). "The FGF7/FGFR2 signaling cascade has been found to upregulate thrombospondin 1 (THBS1), promoting invasion and migration of gastric cancer cells." (PMID 38491511, 2024). "We tried to find the concurrent amplification of FGFR2 and MET in gastric cancer through a search in public cohort data (cbioportal.org), but we were unable to find it." (PMID 38137393, 2023). "Following the success of HER-2-targeted therapy in HER-2 positive gastric cancer, several monoclonal antibodies and small molecules targeting other RTKs such as MET and FGFR2, along with their downstream signaling pathways, have been investigated." (PMID 38137393, 2023). "In this review, we focused on established (PD-L1, HER2, MSI) and emerging biomarkers (FGFR2, CLDN18.2) in gastric cancer, their clinical significance, detection methods, limitations, and molecular agents that target these biomarkers." (PMID 37510761, 2023). "Initially, the NGS was tested in a primary tumor specimen from stomach cancer, where the MET copy number was 14.1 and the FGFR2 copy number was 5.3." (PMID 38137393, 2023). "The expression of FGFR2 and FGFR4 was higher in human stomach cancers than in normal tissues, according to the GEPIA and TCGA datasets." (PMID 36147913, 2022). "FGFR alterations (primarily in FGFR2) are found in approximately 13% of intrahepatic cholangiocarcinomas (CCA), 3% of gallbladder cancers, 9% of gastric cancers in a Western population, and 3% of gastric cancers in an Asian population)." (PMID 35668531, 2022). "FGFR2, Muthy, ABCG2 and TRET are four of the top 19 target genes with the highest connections in the PPI network that are important in the fight against gastric cancer." (PMID 36500601, 2022). "We have demonstrated that MBD1 promoted the progression of gastric cancer by recruiting HDAC3 to form a complex, silencing the expression of anti-tumor miR-5701, and increasing the expression of the miR-5701 targets FGFR2." (PMID 35876658, 2022).
gastric cancer (continued). "The objective of this study was to evaluate the expression status of FGFR2 and HER2 in patients with gastric cancer (GC) or colorectal cancer (CRC)." (PMID 35585358, 2022). "Recently, FGFR2 specific antibodies, FPA144 (NCT02318329) have been developed to treat patients bearing high FGFR2b-overexpressing gastric cancers." (PMID 33633310, 2021). "We previously reported that the conditioned medium derived from gastric fibroblasts stimulates the growth of gastric cancer cells, which are mediated by FGF7/FGFR2 signaling." (PMID 33633310, 2021). "In human gastric carcinomas, FISH analysis results also indicated that FGFR2 amplification was correlated with FGFR2IIIb overexpression and/or FGFR2IIIc overexpression." (PMID 33633310, 2021). "Although SHP2 was expressed in all gastric carcinoma cell lines examined, its tyrosine phosphorylation preferentially occurred in several DGC cell lines with Met or FGFR2 gene amplification." (PMID 34503119, 2021). "Fibroblast growth factor receptor type 2 (FGFR2) has emerged as a key oncogenic factor that regulates gastric cancer (GC) progression, but the underlying mechanism of FGF–FGFR2 signaling pathway remains largely unknown." (PMID 32934314, 2020). "Genomic alterations in RTKs, including EGFR, HER2, FGFR2, and MET, were reported to occur in ~37% of gastric cancer patients." (PMID 32005975, 2020). "Intertumoral heterogeneity among actionable biomarkers including ERBB2, FGFR2 and EGFR has been observed to occur under therapeutic pressure in advanced gastric cancer." (PMID 32158697, 2020). "Overall, amplification, and most likely promoter demethylation also, of FGFR2 and ESRP1 genes correlate well with higher expression levels of both genes in gastric cancers." (PMID 31881796, 2019). "Overall, our study demonstrated that RNAscope and DISH are suitable methods to evaluate FGFR2 status in gastric cancer FFPE tissue slides, allowing evaluation of the intratumor heterogeneity of these FGFR2 biomarkers." (PMID 28852882, 2018). "We previously demonstrated that targeting the Golgi apparatus using an Arf1 inhibitor, M-COPA, exerted a selective antitumor effect on gastric cancers amplifying the RTK genes MET and FGFR2 by downregulating the cell surface expression of such RTKs." (PMID 29416720, 2018). "Experiments in vitro and in vivo were performed to further explore FGFR2 and SPRY2 significance on gastric cancer progression." (PMID 28002800, 2017). "SPRY2 can antagonize FGFR2-induced proliferation and invasion via suppressing ERK phosphorylation in gastric cancer cells, indicating SPRY2 as a potential therapeutic target for gastric adenocarcinoma treatment." (PMID 28002800, 2017). "These mapped with high statistical significance to ten canonical signaling pathways, all of which were less active in low DOK6 gastric cancers: gastrin-CREB, NGF, PDGF, EGFR, ERKs, ERBB4, FGFR2, RAS, VEGFR2 and RAF/MAP kinase." (PMID 29872697, 2017). "A total of 9 passable PDX models were successfully established from 32 gastric cancer xenograft donors, consisting of HER2,cMet and FGFR2 alterations with percentages of 4(12.5%), 8(25.0%) and 1(3.1%) respectively." (PMID 28292264, 2017). "As a well-defined antagonist in FGFR2-induced RAS/ERK activation, ectopic expression of sprouty (SPRY) family was reported in several kinds of cancers except gastric cancer." (PMID 28002800, 2017). "EGFR, ERBB3/HER3, VEGF, PI3K/mTOR, FGFR2 and MET show promise as new targets for gastric cancer treatment." (PMID 29237412, 2017). "A recent genomic study of gastric cancers identified somatic copy number alterations of seven oncogenes involved in tyrosine kinase/MAP-kinase pathways: KRAS, EGFR, HER2, FGFR1, FGFR2, MET and IGF1R." (PMID 27437872, 2016). "FGFR pathway inhibition was examined in three solid tumor lines, the colorectal cancer cell line (NCI-H716), and gastric cancer cell lines (SNU-16 and KATO-III), all these cell lines are FGFR2 amplified." (PMID 27627808, 2016).